PER3 (period circadian regulator 3)
Description:
Originally described as a core component of the circadian clock. The circadian clock, an internal time-keeping system, regulates various physiological processes through the generation of approximately 24 hour circadian rhythms in gene expression, which are translated into rhythms in metabolism and behavior. It is derived from the Latin roots 'circa' (about) and 'diem' (day) and acts as an important regulator of a wide array of physiological functions including metabolism, sleep, body temperature, blood pressure, endocrine, immune, cardiovascular, and renal function. Consists of two major components: the central clock, residing in the suprachiasmatic nucleus (SCN) of the brain, and the peripheral clocks that are present in nearly every tissue and organ system. Both the central and peripheral clocks can be reset by environmental cues, also known as Zeitgebers (German for 'timegivers'). The predominant Zeitgeber for the central clock is light, which is sensed by retina and signals directly to the SCN. The central clock entrains the peripheral clocks through neuronal and hormonal signals, body temperature and feeding-related cues, aligning all clocks with the external light/dark cycle. Circadian rhythms allow an organism to achieve temporal homeostasis with its environment at the molecular level by regulating gene expression to create a peak of protein expression once every 24 hours to control when a particular physiological process is most active with respect to the solar day. Transcription and translation of core clock components (CLOCK, NPAS2, BMAL1, BMAL2, PER1, PER2, PER3, CRY1 and CRY2) plays a critical role in rhythm generation, whereas delays imposed by post-translational modifications (PTMs) are important for determining the period (tau) of the rhythms (tau refers to the period of a rhythm and is the length, in time, of one complete cycle). A diurnal rhythm is synchronized with the day/night cycle, while the ultradian and infradian rhythms have a period shorter and longer than 24 hours, respectively. Disruptions in the circadian rhythms contribute to the pathology of cardiovascular diseases, cancer, metabolic syndromes and aging. A transcription/translation feedback loop (TTFL) forms the core of the molecular circadian clock mechanism. Transcription factors, CLOCK or NPAS2 and BMAL1 or BMAL2, form the positive limb of the feedback loop, act in the form of a heterodimer and activate the transcription of core clock genes and clock-controlled genes (involved in key metabolic processes), harboring E-box elements (5'-CACGTG-3') within their promoters. The core clock genes: PER1/2/3 and CRY1/2 which are transcriptional repressors form the negative limb of the feedback loop and interact with the CLOCK|NPAS2-BMAL1|BMAL2 heterodimer inhibiting its activity and thereby negatively regulating their own expression. This heterodimer also activates nuclear receptors NR1D1, NR1D2, RORA, RORB and RORG, which form a second feedback loop and which activate and repress BMAL1 transcription, respectively. Has a redundant role with the other PER proteins PER1 and PER2 and is not essential for the circadian rhythms maintenance. In contrast, plays an important role in sleep-wake timing and sleep homeostasis probably through the transcriptional regulation of sleep homeostasis-related genes, without influencing circadian parameters. Can bind heme.
Synonyms: GIG13; FASPS3
Tractability: PROTAC: UniProt records ubiquitination sites on it; ubiquitination databases record sites on it.
Gene: Protein-coding gene on chromosome 1 (7,784,291 to 7,845,181, forward strand). Ensembl gene ENSG00000049246.
Subcellular location: Cytoplasm; Nucleus
Subcellular location (Human Protein Atlas): Cytosol
Pathways (Reactome):
Circadian clock: Degradation of CRY and PER proteins; Phosphorylated BMAL1:CLOCK (ARNTL:CLOCK) activates expression of core clock genes; Phosphorylation and nuclear translocation of the CRY:PER:kinase complex; Phosphorylation of CLOCK, acetylation of BMAL1 (ARNTL) at target gene promoters; The CRY:PER:kinase complex represses transactivation by the BMAL:CLOCK (ARNTL:CLOCK) complex
Gene Ontology:
Molecular function: protein binding; transcription cis-regulatory region binding; transcription corepressor binding; kinase binding; ubiquitin protein ligase binding
Biological process: negative regulation of transcription by RNA polymerase II; protein stabilization; regulation of circadian sleep/wake cycle, sleep; circadian regulation of gene expression; entrainment of circadian clock by photoperiod
Cellular component: cytoplasm; cytosol; nucleus
Genetic constraint (gnomAD): Loss-of-function variants: 62 observed, 75.94 expected, observed/expected ratio (o/e) 0.82, 90% interval 0.66 to 1.01. The upper end of that interval is the gene's LOEUF score, 1.01, which puts it in group 4 of 6, group 1 being the genes least tolerant of losing a copy. Missense variants: 1,141 observed, 1,163.4 expected, observed/expected ratio (o/e) 0.98, 90% interval 0.93 to 1.03. Synonymous variants: 481 observed, 464.39 expected, observed/expected ratio (o/e) 1.04, 90% interval 0.96 to 1.12.
Homologues: Orthologues: chimpanzee PER3 (97% identical), macaque PER3 (90% identical), dog PER3 (62% identical), mouse Per3 (60% identical), rat Per3 (59% identical), tropical clawed frog per3 (46% identical), zebrafish per3 (40% identical), Drosophila melanogaster per (17% identical), Caenorhabditis elegans lin-42 (11% identical). Paralogues in human: PER2 (35% identical), PER1 (32% identical).
Diseases named in the same sentence as PER3 in open-access papers:
PER3 is named in the same sentence as 124 diseases in open-access papers, as found by Europe PMC text mining. Sharing a sentence is not in itself a finding about the gene and the disease. The quoted sentences say what the papers report.
breast carcinoma (26 papers, 2010 to 2025). "It is also interesting to note that rs1012477 (located in an intron of PER3) was previously found to be associated with breast cancer and prostate cancer risk." (PMID 40534841, 2025). "It was also shown that breast cancer susceptibility was significantly increased in PER3-deficient mouse models." (PMID 39771050, 2024). "The published datasets were analyzed to better understand the association between PRMT6, PARP1, DDB1, and PER3 in breast cancer." (PMID 36941223, 2023). "The CRY2 genotype of breast cancer patients has also been correlated with ER status, and PER3 loss is associated with recurrent ER+ tumors." (PMID 35163264, 2022). "This idea is supported by our data showing a preferential allelic imbalance at the PER3 locus and by the association found between low PER3 expression levels and worse disease-free survival outcomes in Luminal A breast cancers." (PMID 34508103, 2021). "Our analyses suggest that changes in gene expression in PER3 and its co-expression partners are associated with relapse-free survival in overall and more specifically in luminal A breast cancers." (PMID 34508103, 2021). "They found that a structural variant in the circadian gene PER3 was significantly associated with increased risk of breast cancer and posited it as a potential biomarker for breast cancer." (PMID 33419321, 2020). "One of the first epidemiologic studies correlated PER3 variants with increased risk of breast cancer." (PMID 31303884, 2019). "In the first molecular epidemiologic study correlating a clock gene with the risk of human cancer, a structural variant in the circadian gene PER3 was detected to be significantly associated with increased risk of breast cancer." (PMID 28177907, 2017). "Noticeably, the available data on the PER3 rs1012477 variant also revealed a significant interaction between breast cancer risk and ER/PR status (ER/PR positive)." (PMID 28177907, 2017). "A variable number tandem repeat (VNTR) in the PERIOD3 (PER3) gene has been associated with sleep disorders, differences in diurnal hormone secretion, and increased premenopausal breast cancer risk." (PMID 25501848, 2015). "A recent study among PER3 knockout mice indicated that 36% of the homozygous null variants developed chemically-induced mammary tumors compared to 12% among heterozygotes and 0% among wild-type mice." (PMID 25501848, 2015). "A comprehensive cohort study of 1,690 breast cancer patients demonstrated a significant association between the genotype variations of PER3 gene and radiotherapy side-effects, suggesting the potential of the PER3 gene as a predictor for radiotherapy response." (PMID 38813085, 2024). "Additionally, polymorphisms of rhythm genes, including BMAL1, CRY2, PER1, PER2 and PER3, are associated with susceptibility to breast cancer." (PMID 35180863, 2022). "The expression levels of 32 genes that showed significant co-expression patterns with PER3 in human and murine healthy mammary tissues were significantly associated to relapse-free survival in the complete breast cancer dataset whereas 27 did it in lumA samples." (PMID 34508103, 2021). "In breast cancer, sleep disruption is more prevalent in patients where the tumor cells have lost the short allele of the Per3 gene, but retained the long allele, leading to reduced overall expression of Per3." (PMID 34958429, 2021). "Finally, we investigated the associations between PER3 expression and disease-free survival in breast cancer for each specific intrinsic molecular subtype." (PMID 34508103, 2021). "In addition, women in this exposure group carrying at least one variant allele of several SNPs in the other core circadian genes such as BMAL2, CSNK1E, NPAS2 and PER3 had a noteworthy reduced risk of breast cancer." (PMID 23822714, 2013).
breast carcinoma (continued). "Although there is a paucity of molecular epidemiological data to validate hypotheses, it has been noted that a structural variant of PER3 was associated with the incidence of breast cancer in young women and those that have PER3 variants also have a higher burden of long-term toxicity of treatment." (PMID 35163264, 2022). "These facts taken together with the trend of risk increase observed in our meta-analysis for the 5-repeat allele carriers suggests that that PER3 long allele repeat could be increasing the breast cancer risk of a subset of patients exposed to specific environmental conditions." (PMID 34508103, 2021). "In addition, an average expression signature was constructed using the expression values of those PER3 co-expression partners that were found to be associated with a significant increase or reduction in relapse-free survival in the complete breast cancer dataset." (PMID 34508103, 2021). "Conversely, overexpression of PER3 had an inhibitory effect on these malignant phenotypes of breast cancer cells." (PMID 39771050, 2024). "Researchers conducted cell function experiments on the PER3 gene and found that silencing it increased the ability of breast cancer cells to proliferate, invade, and metastasize in vitro." (PMID 39771050, 2024). "Meanwhile, in breast cancer cells treated with Olaparib, withdrawing PER3 returned PER3 oscillation to baseline." (PMID 36941223, 2023). "In overexpressing PRMT6 cells, Olaparib treatment reduced the proliferation and invasive ability of breast cancer cells compared with the control group, whereas PER3 deletion rescued these effects." (PMID 36941223, 2023). "We concluded that the PRMT6/PARP1/Cullin4B (CUL4B)‐Ring E3 ligase (CRL4B) complex transcriptionally represses PER3 and promotes breast cancer proliferation, invasion, and metastasis." (PMID 36941223, 2023). "We also validated the co‐expression of PARP1, PRMT6, and PER3 in normal breast tissue and three different grades breast cancer tissues using immunofluorescent staining (IF)." (PMID 36941223, 2023). "Olaparib alters circadian clock oscillation by incrementing the amplitude of the clock gene PER3 in breast cancer." (PMID 36941223, 2023). "Elevated PARP1, or reduced PER3 levels, were correlated with poor overall survival in breast cancer patients." (PMID 36941223, 2023). "The expression levels of rhythm genes, such as CLOCK, PER1, PER2, PER3, CRY2, RORC and TIMELESS, are associated with the metastasis-free survival of breast cancer patients." (PMID 35180863, 2022). "Overall changes in PER3 co-expression between healthy mammary tissues and breast cancer were related to energy and lipid metabolism." (PMID 34508103, 2021). "PER3 differential co-expression analysis between LumA and basal array breast cancer samples yielded 556 differentially co-expressed genes." (PMID 34508103, 2021). "Three hundred and twenty genes showed significant differential co-expression with PER3 in the healthy tissue versus luminal A (LumA) breast cancer analysis using D1 data." (PMID 34508103, 2021). "PER3 expression was downregulated in various cancers such as breast cancers, hepatocellular carcinomas, human lung cancer, and colorectal cancer." (PMID 34721627, 2021). "In contrast, the carriers of a dominant genotype of PER3 rs10462020 had a significantly reduced level of mRNA expression in breast cancer tissue p = 0.02." (PMID 31739444, 2019). "In the subjects with three night shifts, SNPs in BMAL1 (rs2278749), BMAL2 (rs2306074), CSNK1E (rs5757037), NPAS2 (rs17024926), PER3 (rs1012477) and MTNR1A (rs131113549) were associated with decreased breast cancer risk." (PMID 23822714, 2013). "Downregulations of PER1, PER2, or PER3 have been observed in various cancers, including oral squamous cell carcinoma, head and neck squamous cell carcinoma, colorectal cancer, breast cancer, ovarian cancer, melanoma, and hematological malignancies." (PMID 38813085, 2024).
breast carcinoma (continued). "Transcriptome analysis from the GEO database indicated that PER3 gene expression could predict outcomes for ER+/HER2-breast cancer patients through multifactor Cox analysis." (PMID 38813085, 2024). "Moreover, knockdown of PRMT6 and PARP1 significantly impeded breast cancer cell invasiveness, whereas constraining PER3 expression restored it to normal levels." (PMID 36941223, 2023). "Our data on this combined germline and somatic genetic analysis of associations between the PER3 polymorphism and breast cancer suggest that the long repeat PER3VNTR allele may influence breast cancer at two different levels." (PMID 34508103, 2021). "We have shown that low levels of both PER3 expression and its robust co-expression partners are associated with a reduction in relapse-free survival in Luminal A breast cancer but not in other subsets of patients." (PMID 34508103, 2021). "The present study mirrors previous investigations that have examined clock gene polymorphisms in conjunction with cancer susceptibility, including one that identified an association between the 5-repeat PER3 VNTR sequence and increased odds of premenopausal breast cancer." (PMID 25501848, 2015). "PER3 is considered a candidate tumor suppressor gene, and the 5/5 PER3 VNTR genotype has been associated with increased premenopausal breast cancer risk, though not consistently." (PMID 25501848, 2015). "Additionally, the deregulated expression of the circadian related genes PER1, PER2 and PER3 in breast cancers has been studied." (PMID 25041817, 2014). "Our data suggest that PER3 alterations could play a significant role in breast cancer." (PMID 34508103, 2021). "Finally, relapse-free survival (RFS) analysis showed that low expression levels of PER3 were linked to a significant lower RSF in luminal A (p = 3 × 10−12) but not in the rest of breast cancer subtypes." (PMID 34508103, 2021). "The PER3 gene, potentially regulated by MEK/ERK signaling, functions as a tumor suppressor in breast cancer initiation and progression." (PMID 41142939, 2025). "Disrupted expression of core circadian genes (BMAL1, CLOCK and PER3) and hub genes such as ACTB, GAPDH and CDK1 suggests that circadian gene dysregulation promotes breast cancer progression and represents a potential therapeutic target." (PMID 41908013, 2025). "While in KIRC and breast cancer, upregulation of CLOCK, ARNTL and PER3 promotes TME inflammation via modulating macrophages and neutrophils infiltration, which leads to worse prognosis." (PMID 37183243, 2023). "Meanwhile, PER3 protein abundance was decreased, and was inversely correlated with the abundance of PRMT6 and PARP1, in breast cancer samples." (PMID 36941223, 2023). "Comparing breast cancer to adjacent tissue, PER1, PER2, PER3, and CRY2 levels are decreased; CLOCK is increased; and CRY1 downregulation was found to escalate directly with breast cancer stage." (PMID 35163264, 2022). "Low values of PER3 expression were found to be significantly associated to worse relapse-free survival outcomes in both, the complete dataset (HR = 0.61, p-val = 8.6 × 10−15) and in LumA samples (HR = 0.51, p-val = 5.3 × 10−11) but not in the rest of breast cancer subtypes." (PMID 34508103, 2021). "Some studies have indicated similar results showing that genes PER1, PER2, PER3, and CRY2 were down-expressed in breast cancer tissues." (PMID 29958276, 2018). "Differential co-expression analysis of PER3 between breast cancer subtypes suggest that PER3 present modest negative correlation with many cell cycle related genes in Luminal A samples but not in the other subtypes, especially in the basal subtype." (PMID 34508103, 2021). "A significantly decreased mRNA level in the breast cancer tissue samples was observed for CRY2 (β-coefficient -0.424, p<0.0001), PER1 (β-coefficient -0.371, p<0.0001), PER2 (β-coefficient -0.149, p = 0.037) and PER3 (β-coefficient -0.231, p = 0.001)." (PMID 29958276, 2018).
breast carcinoma (continued). "Similarly, PER3 and RIZ1 exert inhibitory effects on aggressive phenotypes of breast cancer cells." (PMID 31243265, 2019). "Many of the associations, such as PER3 (rs1012477), CSNK1E (rs1534891) and CLOCK (rs11133373, rs3749474), are novel in relation to breast risk but may not be specific to breast cancer, because they have also been found to be associated with prostate and colorectal cancer risk." (PMID 23822714, 2013). "In more than 95 % of breast cancer tissue from 55 women, expression levels of PER1, PER2, and PER3 were severely disrupted in comparison with adjacent non-cancerous tissue." (PMID 27492458, 2016).